GZMB (granzyme B)
Diseases named in the same sentence as GZMB in open-access papers (continued):
Sharing a sentence is not in itself a finding about the gene and the disease.
Obesity (18 papers, 2014 to 2025). Accumulation of substantial excess body fat. "Decreased GzmB expression was associated with increased viral loads, similar to decreased GzmB expression observed in human NK cells in obesity in the context of cancer." (PMID 40352719, 2025). "Also, decreases in T cell production of effector molecules like IFN-γ and granzyme B is associated with obesity." (PMID 35795152, 2022). "Through differential gene expression analysis, WGCNA, and machine learning methods, we identified three biomarkers (IL6R, GZMB, and MSR1) associated with obesity." (PMID 39502334, 2024). "The ROC curve results also demonstrate high diagnostic value of GZMB (AUC: 0.790), MSR1 (AUC: 0.959), and IL6R (AUC: 0.857) for obesity." (PMID 39502334, 2024). "The established ROC curve results also indicate high diagnostic value of GZMB (AUC: 0.857), MSR1 (AUC: 0.959), and IL6R (AUC: 0.857) for obesity." (PMID 39502334, 2024). "Future studies should aim to investigate the functional roles of IL6R and GZMB, as this could reveal their contributions to obesity and THCA and potentially identify new therapeutic targets." (PMID 39502334, 2024). "In conclusion, our research found that CD40LG and GZMB played important roles in immunity and inflammation modules in the VAT of OSA patients, and pro-inflammatory M1 macrophage in VAT was a hallmark feature in OSA patients independently of obesity." (PMID 36923793, 2023). "In the validation group, GZMB, MSR1, and IL6R were similarly significantly upregulated in adipose tissues of the obesity group." (PMID 39502334, 2024). "Initially, in the training dataset GSE44000, we observed significant upregulation of GZMB, MSR1, and IL6R in adipose tissues of the obesity group." (PMID 39502334, 2024). "Circulating MAITs in obesity and metabolic disease are characterized by increased IL2, granzyme B, IL17, IFNγ, and TNFα, and less IL10 compared to healthy controls." (PMID 38674935, 2024). "In the MC38 model, obesity led to a reduction in IFN-γ+, double-expressing IFN-γ+TNF+, and GzmB+ CD8 T cells." (PMID 35103755, 2022). "Ex vivo ligation of CD3/CD28 for 72 h revealed the presence of granzyme B–producing CD8 + T cells in lean AT, and interestingly, obesity induced a fourfold increase in the proportion of these cells." (PMID 32973799, 2020). "A recent study demonstrated that SIR levels are also correlated with the inflammatory protease circulating granzyme B levels that is increased in type 2 diabetes mellitus (T2DM), and further augmented by obesity in patients." (PMID 24995000, 2014). "Moreover, obesity suppresses the expression of IFN-γ, IFN-β, TNF, and granzyme B (GzmB) in CD8 T cells." (PMID 40863244, 2025). "Consequently, the increase in PD-1+ CD8+ cells by diet-induced obesity resulted in reduced expression of cytotoxic genes such as IFN γ and granzyme B (GzB), suggesting that obesity decreases anti-tumor cytotoxic activity by induction of T cell exhaustion." (PMID 35186923, 2022). "Additionally, some studies report no changes in baseline granzyme B/perforin production by NK cells in obesity." (PMID 41425544, 2025). "The heatmap reveals that GZMB upregulates the expression levels of monocytes, dendritic cells, and eosinophils in obesity, MSR1 upregulates the expression levels of macrophages and natural killer cells in obesity, and IL6R upregulates the expression levels of dendritic cells in obesity." (PMID 39502334, 2024). "However, during obesity the number of peripheral NK cells increased and they were activated with elevated expressions of CD69 and Granzyme B, but had an impaired ability to respond and eliminate target tumor cells, which was highly related to the severity of obesity." (PMID 32765518, 2020).
Obesity (continued). "Furthermore, the influenza vaccine is not as effective in individuals with obesity compared to individuals of healthy weights, potentially in part due to decreased antibody titers, decreased CD8+ T-cell activation, and decreased production of functional proteins IFN-ɣ and granzyme B." (PMID 35795152, 2022).
cervical carcinoma (17 papers, 2014 to 2025). A carcinoma arising from either the exocervical squamous epithelium or the endocervical glandular epithelium. "Similarly to the finding in cervical cancer, GZMB expression was negatively associated with survival in patients with PDAC in the present study." (PMID 36196256, 2022). "GZMB is a component of cytolytic granules within NK cells and was reported to be correlated with cervical cancer." (PMID 37662927, 2023). "For example, there are B cells secreting GZMB in the tumor microenvironment in colorectal, breast, prostate, and cervical cancer, and their role in anti-tumor immunity is different from that of T cells." (PMID 37553332, 2023). "In the tumor tissues of patients with advanced cervical cancer, the expression of GZMB was significantly up-regulated." (PMID 36497244, 2022). "constructed a new prognosis predication model based on 8 risk-related PRGs (GPX4, GSDME, GZMA, GZMB, IL1B, NOD1, PRKACA, and TNF) in cervical cancer, which had good predictive ability (AUC = 0.794)." (PMID 35912258, 2022). "An immunocorrelation analysis showed that the PRGs, including CHMP4C, TNF and GZMB, were closely related to the tumor immune microenvironment, thereby influencing the progression of cervical cancer." (PMID 36497244, 2022). "Moreover, the expression of GZMB in tumor tissues was significantly up-regulated and this expression of GZMB negatively correlated with the survival of patients with cervical cancer." (PMID 36497244, 2022). "Similar dynamic characteristics were also observed with another target cancer cell line, HeLa (derived from cervical cancer), indicating that granzyme-B independent mechanism is responsible to activate major cytotoxicity of primary NK cell against at least some mammalian cancer targets." (PMID 27323411, 2016). "Therefore, we identified 52 PRGs from the TCGA database and screened three Differentially Expressed Pyroptosis-Related Genes (DEPRGs) in the prognosis of cervical cancer: CHMP4C, GZMB, TNF." (PMID 35574296, 2022). "Moreover, the production of cytolytic granzyme B was tested and results indicated that CD8+ T cells incubated with YTHDF1 high-expression transfected cervical cancer cells secreted significantly lower amounts of granzyme-B than that YTHDF1 silencing transfection." (PMID 39557826, 2024). "Moreover, the lower the expression of GZMB as a protective factor, the worse the prognosis was; thus, TRIM52-AS1 may be concluded to promote the progression of cervical cancer through miR-378a/GZMB, which needs to be studied further for validation." (PMID 34837692, 2021).
systemic lupus erythematosus (17 papers, 2012 to 2025). An autoimmune multi-organ disease typically associated with vasculopathy and autoantibody production. "IL-21, a cytokine implicated in lupus pathogenesis, can induce granzyme B production in human pDCs, enabling them to promote keratinocyte apoptosis in cooperation with NK cells." (PMID 41008557, 2025). "cSiO2 also elicited extracellular granzyme B, which has been linked to lupus pathogenesis by cleaving autoantigens and exposing neoepitopes, as well as ACE and the aspartic acid protease renin 1, two key enzymes in the renin-angiotensin system." (PMID 35126352, 2021). "Type 1 IFNs increase the cytotoxic function of T cells by upregulating IFN regulatory factor 7 (IRF7) expression, which is responsible for GzmB production in AID, such as autoimmune kidney disease in mice and systemic lupus erythematosus (SLE) in humans and associated glomerulonephritis." (PMID 41009359, 2025). "The maintenance of inflammation in Systemic Lupus Erythematosus (SLE) patients may be aided by increased granzyme B secretion from NK and NKT-like cells in active SLE patients, which is further exacerbated by circulating IL-15." (PMID 36769064, 2023). "ELISA assay showed marked increase of perforin and granzyme B derived from the NKG2D+CD4+ T cells co-cultured with lupus serum that stimulated Treg cells, indicating that NKG2D+CD4+ T cells could kill target cells by secreting cytotoxic mediators in vitro." (PMID 28455530, 2017). "In addition, they exert tolerogenic functions e.g. via indoleamine-pyrrole 2,3-dioxygenase or granzyme B, but also play an important role in the pathophysiology of different autoimmune diseases like psoriasis and systemic lupus erythematosus (SLE)." (PMID 26252890, 2015). "On the one hand, CD8+ T cells in the peripheral blood of SLE patients often have reduced granzyme B and perforin production and exhibit impaired cytolytic function, which impairs the removal of autoreactive B cells and increases autoantibodies, accelerating the onset of lupus." (PMID 36032079, 2022). "Finally, the percentages of CD161+ iNKT cells, perforin and granzyme B expression of expanded iNKT cells correlated with complement C3 levels, thus may confer protection against lupus flare." (PMID 34936686, 2021). "Interestingly, Human Parvovirus B19 specific GzmB producing CD4+ T cells may contribute to RA and systemic lupus erythematosus (SLE) associated with chronic B19 infection." (PMID 32226027, 2020).
diabetes (15 papers, 2008 to 2026). "The incidence of spontaneous diabetes in granzyme B-deficient mice was the same as wild-type NOD mice." (PMID 22792290, 2012). "A cohort of female NOD (n = 35) and granzyme B-deficient NOD (n = 19) mice were observed for 300 days for the incidence of spontaneous diabetes." (PMID 22792290, 2012). "The upregulation of Foxp3, CD103 and granzyme B expression may reflect restoration of a fully activated regulatory cell population, which may be crucial for the regulation of pathogenic cells and prevention of diabetes development." (PMID 19011680, 2008). "In keeping with those findings we show that IFNAR1 deficient 8.3 mice also have normal diabetes incidence and CD8+ T cells have normal levels of granzyme B expression after transfer and isolation from NOD islets." (PMID 31653894, 2019). "Furthermore, increased serum levels of granzyme B have been independently associated with T2D diagnosis, underscoring the potential significance of CD4 Tcyt cells in the pathophysiology of diabetes." (PMID 39072276, 2024). "The main purpose of this study was to determine whether GzmB contributes to the pathogenesis of chronic wound healing in individuals with diabetes." (PMID 25299783, 2014). "Granzyme B−/− mice developed diabetes at the same rate and incidence as NOD mice." (PMID 22792290, 2012). "We did not observe any effect of granzyme B deficiency on the incidence of diabetes, indicating that there is redundancy in the use of granzymes by CTL to kill target cells." (PMID 22792290, 2012). "Both ND and diabetes groups contained similar frequencies of TNF‐ and granzyme B‐producing CD8+ T cells, with IFNγ and IL‐2 production being significantly increased in T1D and T2D compared with ND, respectively." (PMID 41367201, 2025). "Notably, a reduced percentage of PIL expressed granzyme B when RIP-gp mice were given HIF-1α-Tg BMDCs, coinciding with the limited induction of islet cell death and reduced frequency of diabetes induction in the RIP-gp model." (PMID 33382742, 2020). "In the current study we show that granzyme B may be important for homeostasis of CD8+ T cells in the periphery, for efficient proliferation of CD8+ T cells in the PLN in the early stages of diabetes pathogenesis, and for homing of primed CTL into the pancreas." (PMID 22792290, 2012). "In contrast, the incidence of diabetes in the absence of granzyme B was the same as wild-type NOD mice." (PMID 22792290, 2012). "Moreover, B and T cell responses are altered in people with diabetes in several ways for instance, reduced expression of co-stimulatory molecules (CD69, CD28, CD40 ligand) or interleukin-12 receptor on T cells which leads to lower production of interferon and granzyme B." (PMID 36105809, 2022).
myeloma (15 papers, 2018 to 2025). "BCMA-CAR-NK cells also secreted significantly more IFN-gamma and Granzyme B than NK cells against multiple myeloma target cells." (PMID 37686170, 2023). "Anti-myeloma specific T cell responses with increased secretion of IFN-γ, perforin and granzyme B were observed in a clinical trial of myeloma patients that received lenalidomide as consolidation therapy after ASCT." (PMID 33746969, 2021). "In this case, T cell-myeloma cell linkage is followed by CD4+/CD8+ activation to cause secretion of interferon-γ, in addition to perforin and granzyme B." (PMID 30544512, 2018). "NK cell function can also be affected by the levels of its cytotoxic granule proteins and cytokines, as seen, for example, in the TME of multiple myeloma, where inhibition of NK cell activity occurred via lower levels of perforin and granzyme B, despite unchanged degranulation." (PMID 33513976, 2021). "Bone marrow myeloma cells were identified using PE‐CD138, while NK/NK‐92 cells were stained with antibodies targeting Perforin (APC anti‐human), Granzyme B (FITC anti‐human/mouse), and NKG2D (Percp Cy5.5)." (PMID 40557764, 2025). "When co-cocultured with RPMI-8226 myeloma cells with YBX1 knockdown, the frequencies of IFN-γ+ and GZMB+ cells among CD8+ T cells were significantly higher than those in CD8+ T cells co-cultured with control RPMI-8226 cells." (PMID 36717896, 2023). "BCMA-CAR-NK cells after transfection with CAR mRNA-LNPs killed multiple myeloma RPMI8226 and MM1S cells and secreted IFN-gamma and Granzyme B in a dose-dependent manner in vitro." (PMID 37686170, 2023). "ATC from up to 8 normal donors were armed with various concentrations of CS1 BiAb and tested against 5 myeloma cells lines for CS1-BATs-mediated killing and release of Th1 cytokines, chemokines and granzyme B." (PMID 32432032, 2020). "BCMA-CAR-NK effectively killed multiple myeloma cells and secreted a high level of IFN-gamma and Granzyme B. CD19-CAR-NK cells effectively killed leukemia cancer cells and secreted high levels of IFN-gamma and Granzyme B in vitro." (PMID 37686170, 2023). "As an anti-myeloma effect, we and others have demonstrated that NK cell cytotoxicity against primary myeloma cells depends on expression of NKG2D and DNAM-1, as well as perforin/granzyme B." (PMID 32231116, 2020). "Notably, IL-15 mDCs showed very good stimulatory capacity for autologous CIK cells, a higher proportion of CD44+, IFN-γ+, granzyme B+, and NKG2D in CIK cells, and a higher cytotoxicity of CIK cells against cancer cell lines and patient autologous primary myeloma cells." (PMID 35413499, 2022).
Autoimmunity (14 papers, 2012 to 2024). The occurrence of an immune reaction against the organism's own cells or tissues. "A hypothesis concerning autoimmunity suggests that the proteolytic cleavage by granzyme B can convert a tolerized self-antigen to novel fragments with newly exposed cryptic determinants, thus triggering the autoimmune response." (PMID 38384322, 2023). "Of note, CD8+ T cells propagates autoimmunity via granzyme-B-generated unique autoantigen fragments; whereas, C1q limits tissue damage and autoimmunity by mediating effector CD8+ T cells, providing biological insight into an interconnectivity between C1q and granzyme B29." (PMID 36443341, 2022). "Granzyme B (GZMB) is a serine protease involved in inflammatory responses and autoimmunity." (PMID 36118358, 2022). "Thus, Ag-recognition by CD8+ T cell inducing CD8+ T cell mediated, Granzyme B-dependent BBB breakdown is not essential for immune cell infiltration and focal BBB breakdown in the ODC-OVA model of autoimmune neuroinflammation." (PMID 37253744, 2023).
chronic obstructive pulmonary disease (14 papers, 2011 to 2025). A chronic and progressive lung disorder characterized by the loss of elasticity of the bronchial tree and the air sacs, destruction of the air sacs wall, thickening of the bronchial wall, and mucous accumulation in the bronchial tree. "While granzyme H remains less well studied in terms of respiratory disease, granzyme B has been implicated in e.g. chronic obstructive pulmonary disease, and fatal asthma." (PMID 37936126, 2023). "In chronic obstructive pulmonary disease (COPD), GZMB is highly expressed in type II alveolar epithelial cells, monocytes, and granulocytes, indicating its role as a key mediator in non-immune cells." (PMID 41244830, 2025). "We have shown that chronic obstructive pulmonary disease (COPD) is associated with increased production of pro-inflammatory cytokines and the cytotoxic mediator, granzyme B by peripheral blood steroid resistant CD28nullCD137 + CD8+ T cells and granzyme B by NKT-like and NK cells." (PMID 24885856, 2014). "In NSCLC patients with chronic obstructive pulmonary disease (COPD), although the number of tumor‐infiltrating CD8+ MAIT cells increases, they show a functionally exhausted phenotype, characterized by reduced secretion of GZMB and IFN‐γ, and increased expression of the immune checkpoint PD‐1." (PMID 41179703, 2025). "Type-1 helper (Th1) lymphocytes and CD8+ T cells are elevated in a number of inflammatory diseases including chronic obstructive pulmonary disease (COPD) where these cells are located at the sites of airways obstruction and may contribute to emphysema via the production of granzyme B and perforins." (PMID 26090665, 2015).
multiple sclerosis (14 papers, 2010 to 2024). A progressive autoimmune disorder affecting the central nervous system resulting in demyelination. "Recently, GZMB-producing cells have been suggested to play a role in the disease progression in multiple sclerosis." (PMID 38978729, 2024). "Although the expression of granzyme B (GZMB) is linked to the pathogenic signature of T cells in experimental autoimmune encephalomyelitis (EAE) and multiple sclerosis, its precise role in multiple sclerosis is still under investigation." (PMID 26714756, 2015). "Our findings establish that TCF-1 expression in human CD4+ T cells is linked to multiple sclerosis and that treatment with FTY720 increases TCF-1 expression, which regulates IFN-γ and GZMB production." (PMID 26714756, 2015). "Furthermore, GzmB’s neurotoxic effects appear to transcend T cell-delivered intracellular cytotoxic mechanism in neurological diseases such as Multiple Sclerosis (MS), wherein GzmB was shown to induce neurotoxicity through interacting with the membrane bound receptors." (PMID 38846935, 2024). "This selectivity profile of probe H5 may find application for monitoring GzmB activity in other diseases where the activation state of immune cells is currently under investigation, such as Epstein-Barr virus-mediated multiple sclerosis and chronic obstructive pulmonary disease." (PMID 35501326, 2022). "Assessing 15 representative signature genes in patients with multiple sclerosis, we find that TH1/17 cells have elevated expression of CXCR3 and reduced expression of IFNG, CCL3, CLL4, GZMB, and IL10 compared to healthy controls." (PMID 29150604, 2017). "CD8 cells in gray matter might have a role in tissue destruction by cytotoxic cytokines, the cytotoxic molecules granzyme B, and nitric oxide (NO), resembling the role of CD8 cells in multiple sclerosis." (PMID 21062492, 2010). "Similarly, in multiple sclerosis, CD8+ T cells from active lesions exhibit a tissue-resident memory phenotype (CD69, CD103, PD-1, CD49a) associated with an intermediate expression of GPR56 without granzyme B expression." (PMID 35831277, 2022).